IDH1 (isocitrate dehydrogenase (NADP(+)) 1)
Diseases named in the same sentence as IDH1 in open-access papers (continued):
Sharing a sentence is not in itself a finding about the gene and the disease.
glioma (continued). "While IDH1/IDH2 gliomas could be readily identified with 2-HG23, other types of gliomas might not be diagnosed with MS analysis of a single-compound biomarkers, which also applies for most of the cases for cancer diseases." (PMID 40860133, 2025). "Mutations in IDH1 and IDH2 are essential for glioma classification and prognosis." (PMID 41154393, 2025). "In gliomas lacking IDH1/2 mutations and 1p/19q co-deletion, elevated ADORA1 expression was observed, suggesting a negative correlation with prognosis." (PMID 40376586, 2025). "Among tumor genetic mutations, IDH1 mutations and MGMT methylation are negatively correlated with the occurrence of VTE, and these two genetic mutations have also been proven to be negatively correlated with the occurrence of VTE in adult gliomas." (PMID 40873733, 2025). "The prognosis of gliomas is significantly affected by these molecular alterations, such as whether IDH1, IDH2, EGFR, CDKN2A, and CDKN2B are altered for adult‐type gliomas, and whether H3 K27 and H3 G34 are altered for pediatric‐type gliomas." (PMID 39804195, 2025). "Notably, mutations in IDH1 and IDH2 are well-characterized in lower-grade gliomas and secondary GBM, leading to the production of the oncometabolite 2-hydroxyglutarate (2-HG), which contributes to epigenetic dysregulation and tumorigenesis." (PMID 40282990, 2025). "IDH1-mutant gliomas are now classified separately as astrocytomas (Grades II-IV)." (PMID 40223032, 2025). "IDH1 mutation may lead to impaired type I IFN response and enhance the susceptibility of gliomas to VSVΔ51 infection." (PMID 41296382, 2025). "In the IDH1 wild-type cohort, 21 cases (43.8%) had high-grade glioma (HGG) lesions, comprising 12 cases (25.0%) of glioblastoma, 4 cases (8.3%) of anaplastic astrocytoma, 3 cases (6.3%) of anaplastic oligodendroglioma, 1 case (2.1%) of gliosarcoma, and 1 case (2.1%) of glioblastoma multiforme." (PMID 40944023, 2025). "Gliomas are classified into three broad groups depending on the deletion status of chromosomal arms 1p and 12q, and the mutation status of the citric acid (TCA) cycle enzyme isocitrate dehydrogenase 1 (IDH1) or the mitochondrial IDH2." (PMID 41002991, 2025). "However, gain-of-function mutations in IDH1 or IDH2 convert α-KG into D-2-HG, leading to its pathological accumulation in various cancers such as acute myeloid leukemia (AML), glioma, chondrosarcoma, and cholangiocarcinoma." (PMID 40931345, 2025). "Among glioma subtypes, IDH1/2 mutant glioma has undergone one of the most significant reclassifications in the shift from histopathologic to molecular criteria, with nearly half of these tumors formerly diagnosed as glioblastoma or other non-astrocytic gliomas." (PMID 40949165, 2025). "Although we characterized prognostic indicators for glioblastoma, IDH1/2-mutant astrocytoma, and oligodendroglioma, we were unable to comprehensively analyze molecular features for the pediatric-type and other IDH1/2-wild-type gliomas given the small sample sizes." (PMID 39164213, 2025). "Notably, chromosomal 7+/10− alterations (encompassing EGFR and PTEN loci) were rare in IDH1/2-mutant gliomas (1.0% in high-grade gliomas)." (PMID 41377022, 2025). "IDH1 improvements cause hypermethylation related to prudent gliomas and enhanced endurance, as opposed to a little hypomethylated poor survival gathering." (PMID 40792048, 2025). "Intriguingly, this study revealed that NSUN5 could act as an immune therapy target to transform glioma into a “warm tumour” and lead to impressive therapeutic outcomes when NSUN5 is restored in IDH1-R132H mutant glioma cells." (PMID 40860147, 2025). "Age stratification reinforced the observed patterns: 74.7% of frontal lobe gliomas in younger patients (<46 years) carried IDH1/2 mutation, whereas 91.4% of temporal lobe and 100% of thalamic/basal ganglia tumors in older patients (≥46 years) belonged to the IDH1/2-wild-type glioma subtype." (PMID 41377022, 2025).
glioma (continued). "IDH1 status was not routinely tested in this study but younger patients and those with histological features of low-grade glioma were investigated regarding IDH1 mutation and those patients were excluded." (PMID 39992571, 2025). "Unlike IDH1-wildtype gliomas, IDH1 (R132H) mutations suppress PD-L1 expression through DNA hypermethylation, leading to a less immunosuppressive microenvironment." (PMID 39906459, 2025). "Amongst all IDH1/2-mutant gliomas, 64.1% were MGMT methylated." (PMID 39164213, 2025). "A striking progression has been the joining of atomic markers such as IDH1/2 transformations, MGMT promoter methylation, EGFR amplification/mutations, and 1p/19q codeletion into the symptomatic criteria for gliomas, as laid out by the WHO CNS tumor classifications." (PMID 41311621, 2025). "Gliomas, including GBM, are classified as isocitrate dehydrogenase (IDH)-mutant or IDH-wild type based on whether they harbour mutations in IDH1 or IDH2." (PMID 39796278, 2025). "Multiple ML algorithms, including Decision Tree (DT), K-Nearest Neighbor (KNN), Support Vector Machine (SVM), and Ensemble models, have demonstrated significant potential in IDH1 classification, offering an objective and reproducible method for glioma characterization." (PMID 40299088, 2025). "Moreover, the proportions of IDH1 and TERT promoter mutations were higher in neocortical gliomas than in mesocortical gliomas (67.9% vs. 31.6%, p < 0.01 and 68.4% vs. 25.0%, p < 0.001, respectively)." (PMID 40149633, 2025). "Consequently, the overexpression of mutant IDH1 or D2HG sensitizes glioma cells to infection by oncolytic viruses such as VSVΔ51, thereby promoting viral replication and enhancing therapeutic efficacy." (PMID 40426960, 2025). "Notably, breast cancer seldom exhibits mutations in IDH1 and IDH2, which are known to drive 2HG accumulation in gliomas and leukemia, suggesting alternative mechanisms are responsible for the elevated 2HG levels observed in breast cancer." (PMID 39910592, 2025). "Additionally, another investigation revealed that D2HG, a metabolite produced as a result of IDH1 mutations, impedes the IFN antiviral response in glioma cells, thereby increasing their sensitivity to OV therapy." (PMID 40698086, 2025). "In a cohort of 433 patients with IDH1-mutated grade 2–3 gliomas, approximately 9.9% had non-canonical mutations, and presented with younger age at diagnosis and favorable prognosis (198.6 months vs. 138.5 months; p < 0.05)." (PMID 41346390, 2025). "Notably, IDH1/2-mutant gliomas (favorable prognostic subtype) were significantly enriched in the Low-risk group." (PMID 41169364, 2025). "In addition, on the glioma data set from TCIA, our model achieved a accuracy of 90.9% in the grading of glioma and a accuracy of 93.94% in the classification of glioma IDH1 mutation status." (PMID 40127071, 2025). "Clinical trials, including the phase 3 INDIGO (INdividualized Treatment for IDH1-mutant Glioma With Vorasidenib) study, have demonstrated that Vorasidenib significantly prolongs PFS in patients with WHO grade 2 IDH-mutant gliomas, delaying the need for more invasive therapeutic interventions." (PMID 41008917, 2025). "In addition, IDH1 mutant gliomas exhibit an “immune-cold” microenvironment with abundant microglia, moderate myeloid cells, minimal B cells, and T cells, showing less immunoreaction than IDH wild-type (WT) counterparts." (PMID 41367876, 2025). "Indeed, one study has shown that IDH1-mutant glioma cells are hypersensitive to DHODH-targeting compounds in using a chemical synthetic lethality screen." (PMID 39329757, 2024). "Therefore, IDH1-mutant gliomas demonstrate a high level of oncometabolite D-2-hydroxyglutarate, which causes an increase in migration activity through the PI3K/AKT/mTOR pathway and morphology changes." (PMID 39596246, 2024).
glioma (continued). "Protein expression in mutant IDH1 glioma cells is downregulated compared to IDH1-wildtype cells, which may account for the lower APT signal seen in IDH-mutant gliomas." (PMID 39272871, 2024). "In other work, it was shown that copy number variation (CNV) was more frequent in recurrent tumors and CDKN2A/B loss was significantly enriched in the sample, but that study included IDH1/2 mutant glioma, where CDKN2A/B deletion is a marker of tumor progression." (PMID 39684714, 2024). "A pharmacological blockade of mutated IDH1 impaired the growth of IDH1mut but not IDH1-wild-type, glioma cells." (PMID 39123479, 2024). "Moreover, our external database validation revealed lower Itgb4 expression in IDH1-mutant gliomas, correlating with a more favorable prognosis." (PMID 38982076, 2024). "REST knockdown differently impacted invasion of the parental or IDH1 mutant glioma cells." (PMID 38711090, 2024). "We tested D-2HG levels in 14 IDH1-mutant and 18 IDH1 wild-type glioma tissues using HPLC-MS/MS." (PMID 38982076, 2024). "The absence of the altered DNA sequence variants of IDH1/2 in gliomas is a sign of high grade (HGG)." (PMID 39768176, 2024). "Even if CNS WHO grade 4 gliomas have mutant IDH1/2, they may have poor clinical outcomes because of CDKN2A deletion." (PMID 39457569, 2024). "The IDH1 mutation impeded the maturation of astrocytes with low OGDH, but we found that it did not alter the expression of GFAP, Nestin, CD133, and CD44 in U87 and U251 glioma cells." (PMID 39872214, 2024). "Mutations in IDH1 and IDH2 are common in cancers like gliomas and acute myeloid leukemia." (PMID 39765841, 2024). "Panobinostat was also found to compound to inhibit growth in IDH1 mutant glioma lines." (PMID 39596840, 2024). "In addition to lower levels of BCAAs, IDH1 mutant glioma tissue contains decreased concentrations of the amino acids glycine and serine." (PMID 39596840, 2024). "The evaluation of IDH1 and ATRX status in gliomas has both diagnostic and prognostic value as it helps in differentiating gliomas from reactive gliosis, primary glioblastoma (GB) from secondary glioblastoma, and pilocytic astrocytoma (PA) WHO grade 1 from grade 2 astrocytoma." (PMID 39192927, 2024). "In patients with recurrent high-grade gliomas, IDH1/2 mutations were predictors of any type of treatment but not survival from the first progression." (PMID 39049072, 2024). "A previous study showed that IDH1 wild-type glioma was prone to have a worse prognosis." (PMID 37713112, 2024). "However, mutant IDH1R132H exhibits impaired sialidase activity and delayed killing in glioma cells, underscoring the complexity of IDH1-mediated immunotherapy in glioma tumours." (PMID 38660136, 2024). "Diffuse IDH1/2 wt gliomas are a heterogeneous group of tumors, which in most cases will now be classified as glioblastomas, IDH-wildtype (CNS WHO grade 4) after performing the required molecular diagnostic workup according to the current WHO classification 2021." (PMID 38326661, 2024). "IDH1 mutant and MGMT promoter methylated gliomas were also associated with a frontal lobe location." (PMID 39767640, 2024). "Together, we conclude that in IDH1 MT glioma cell lines, VPA may work through FASN to inhibit cell cycle and anti-apoptotic genes." (PMID 39149696, 2024). "IDH1 MT glioma cell lines had a slightly lower IC50 for VPA compared to IDH1 WT cell lines (WTIC50 = 1.23; MTIC50 = 0.96), and the hill slope between the two dose–response curves were statistically significant (WTHill Slope = −0.80; MTHill Slope = −1.68; 0.0032)." (PMID 39149696, 2024). "IDH1 mutant and MGMT methylated gliomas were associated with frontal lobe location." (PMID 39767640, 2024).
glioma (continued). "For instance, a recent study using large public datasets from The Cancer Genome Atlas and the EBRAINS brain tumor atlas, comprised primarily of tumors from white patients, showed a 16.0% performance gap in the prediction of IDH1 status in gliomas from black vs. white patients." (PMID 38893099, 2024). "In this study, we utilized IDH1 as a target because it is an important biomarker in gliomas." (PMID 38566776, 2024). "In this paper, we aimed to classify the presence or absence of the IDH1 mutation using WSIs and clinical data of glioma patients." (PMID 39038392, 2024). "This reinforces the importance of IDH1 as a prognostic indicator in glioma management." (PMID 39348350, 2024). "Notably, the nuclear localization of FABP7 has been linked to glioma progression, particularly in oncogene-mutated aggressive subtypes, such as EGFR-amplified and IDH1 wild-type GBM." (PMID 39596296, 2024). "18F-FDG uptake in IDH1-mutant gliomas is significantly lower than that in IDH1 wild-type gliomas." (PMID 38932755, 2024). "Notably, the expression of LINC00475 was significantly higher in IDH1 wild-type gliomas compared to IDH1 mutant gliomas." (PMID 38405130, 2024). "In addition to in vitro studies, we show that VPA improved the survival of mice in vivo in two separate models of IDH1 MT glioma." (PMID 39149696, 2024). "Next, we tested the efficacy of HDACi’s in a syngeneic murine IDH1 (mIDH1) glioma model." (PMID 39149696, 2024). "Both IDH1-mutant and wild-type murine gliomas reached the tumor morbidity end stage with a median survival of 40 days post-injection, suggesting the IDH1 mutation did not facilitate or inhibit gliomagenesis in this co-delivery model." (PMID 38334611, 2024). "Moreover, repeat transduction enabled the creation of a cell model that originates from primary patient IDH1-mutant glioma cells converted to an IDH1 WT status." (PMID 39605316, 2024). "Hence, it is possible that in order to overcome the metabolic flexibility of cancer cells, dual targeting of FASN by both VPA and TVB-2640 is potentially an effective therapeutic approach for IDH1 MT glioma." (PMID 39149696, 2024). "There is evidence that c-Myc activation is involved in the progression of IDH1-mutant glioma." (PMID 38786726, 2024). "Furthermore, the expression level of ELAVL2 was low in gliomas with wild-type isocitrate dehydrogenase 1 (IDH1) gene, which plays a critical role in glioma progression." (PMID 38548861, 2024). "At a clinical level, glioma patients carrying mutant IDH1 respond better to antitumor therapies." (PMID 39457600, 2024). "It has been shown to improve the prognosis of IDH1‐mutant glioma." (PMID 39491527, 2024). "Certain clinical prognostic factors (such as age, gender, immunohistochemical subtypes, infiltration site, tumor size, EOR, BMI, ADC value, ECOG score, etc.)and biological prognostic factors (such as ki-67, IDH1, IDH2, MGMT, etc.)have been shown to predict the risk of recurrence in glioma patients." (PMID 38967893, 2024). "Three IDH1 mutant glioma models, including human glioma xenografts in mice, cultured glioma cell lines and human glioma biopsies, showed a distinct phospholipid profile characterized by low levels of phosphoethanolamine and heightened levels of phosphatidylcholine." (PMID 39596840, 2024). "Given that D-2HG reportedly possesses a promising anti-glioma effect, we hypothesized that a synergistic relationship might exist between D-2HG and TMZ, rendering IDH1-mutant glioma patients more sensitive to TMZ treatment." (PMID 38982076, 2024). "Histologically, most of the rat gliomas resemble diffuse low-grade gliomas in humans and such gliomas that do not harbor IDH1/2 mutations in humans are known to have poor prognosis." (PMID 38232086, 2024).
glioma (continued). "Although Tau showed a negative effect in AD, PD, and breast cancer, its opposite function can be observed in IDH1‐mutant glioma and hsa_circ_0001546‐downregulated EOC, which means that genetic differences in various diseases should be considered in the clinical use of Tau inhibitors." (PMID 38634567, 2024). "IDH1 and IDH2 mutational status is a critical biomarker in the evaluation of glioma." (PMID 38796421, 2024). "Overall, IDH1-mutant gliomas show lower amino acid radiotracer uptake than IDH1-wildtype glioma." (PMID 38932755, 2024). "Notably, our study revealed a significant correlation between IDH1 wildtype genotype, 1p/19p co-deletion, and MGMT promoter methylation status in patients with glioma and a high-risk score." (PMID 39574472, 2024). "No mutations were detected in rat gliomas that had homology to the human IDH1 p.132R or IDH2 p.172R mutations suggesting that rat gliomas are primarily wild-type for IDH hotspot mutations implicated in human gliomas." (PMID 38232086, 2024). "This subset of progressed gliomas exhibiting a loss of IDH1 heterozygosity (resulting in reduced D-2-HG generation like that seen in BT142 cells) are thus likely to show sensitivity to FTO inhibitors, similarly to IDH1wt gliomas." (PMID 38445960, 2024). "In the context of gliomas, PTBP1 expression correlates with WHO grade and IDH1 mutation status." (PMID 38918441, 2024). "Surprisingly, no mutations were detected in Idh1, Idh2 and Braf genes that matched to orthologous hot spot mutations in human gliomas and no mutations were observed in spontaneous gliomas (0/4, data not presented)." (PMID 38232086, 2024). "Glioma patients with both the IDH1 mutation and MGMT methylation (3.0% of all patients) had the best overall survival, followed by patients with an IDH1 mutation and unmethylated MGMT promoter (1.0%), then by patients with MGMT promoter methylation and IDH1 wildtype (55.4%)." (PMID 39767640, 2024). "Furthermore, the use of isocitrate dehydrogenase 1 (IDH1) inhibitors is very limited, despite IDH1 being known as one of the most promising biomarkers for glioma diagnosis and prognosis." (PMID 39189437, 2024). "While this approach efficiently addresses a large subset of glioma patients, it does not apply to BT without IDH1 mutations." (PMID 39529768, 2024). "Notably, mutations in the IDH1 and IDH2 genes are recognized for their role in lower-grade gliomas and secondary glioblastomas, offering prognostic and therapeutic implications." (PMID 39397895, 2024). "The occurrence of 1p/19q co-deletion is predominantly observed in IDH1-mutant gliomas." (PMID 38405130, 2024). "Another strategy to target IDH1 genetic alterations in gliomas is the development of vaccines." (PMID 38763973, 2024). "Additionally, pharmacokinetic and metabolism studies were conducted in naïve mice and dynamic PET imaging was performed in a preclinical rat model of orthotopic glioma overexpressing the mutant IDH1R132H or the wild-type IDH1." (PMID 37982850, 2024). "Clinical data from over 2500 glioma patients in our study confirms that those with IDH1 mutations exhibit enhanced responsiveness to TMZ chemotherapy and a significantly better prognosis compared to IDH1 wild-type patients." (PMID 38982076, 2024). "Mutations in IDH1 and, less frequently, IDH2 now define a secondary glioblastoma (low-grade gliomas that eventually underwent a malignant transformation), whereas the IDH1 wild-type is considered to be a primary glioblastoma that arose as a higher-grade tumour." (PMID 39767640, 2024). "Interestingly, the absence or rarity of mutations in IDH1 R132 and IDH2 R172 was also demonstrated in gliomas from dogs, another important model system with significant human relevance." (PMID 38232086, 2024).